STAT3 (signal transducer and activator of transcription 3)
Diseases named in the same sentence as STAT3 in open-access papers (continued):
Sharing a sentence is not in itself a finding about the gene and the disease.
tumor (continued). "Furthermore, some tumor-derived molecules (VEGF, IL-6) enhance the expression of STAT-3 in DCs." (PMID 22110524, 2011). "Seemingly, not merely STAT3 is involved but also a number of inflammatory cytokines does play critical roles in this process and many reports indicate that IL-17 in the context of inflammations exerts tumor promoting effects." (PMID 21943203, 2011). "Although STAT3 has been most extensively studied as a tumor-promoting factor in GBM, evidence has recently emerged to suggest that it may act alternately as a protumorigenic factor or a tumor suppressor based on the genetic background of the tumor." (PMID 22190972, 2011). "However, in vivo experiment demonstrated it took no more than 72 hours that most of Adv-Stat3(-)-loaded MSCs have already arrived at the tumor sites." (PMID 22054049, 2011). "Given that expression of IL-6, IL-8, MMP2, and VEGF increased in parallel with STAT3 and AKT activation in HCC cells treated with IL-17, STAT3, and AKT signaling may play important roles in inducing these proinvasive factors and hence tumor progression." (PMID 22171994, 2011). "None of p-EGFR, p-Akt, or p-Stat3 were seen in tissue adjacent to the tumor or normal skin." (PMID 21197106, 2011). "Compared to the control group, tumor growth was inhibited by Adv-Stat3(-) but not MSC treatment." (PMID 22054049, 2011). "Furthermore, when Stat3 is inhibited, tumor cells will no longer express proangiogenic mediators in response to IL-6R signaling." (PMID 20204067, 2010). "Although STAT3-mediated gene expression signature is mostly consistent with tumour cell survival and proliferation, it varies in different tumour types, and a core activity determining addiction to STAT3 by a wide spectrum of biologically distinct tumors has not yet been identified." (PMID 21084727, 2010). "It is worthwhile to consider whether Stat3-driven tumours also develop addictions to non-oncogene pathways that are amenable to therapeutic interference." (PMID 20478049, 2010). "Small cell lung cancer tumour and cellular models for in vitro investigation have been shown to be heterogeneous; however, some common features can be described: all analysed SCLC cell lines showed constitutive STAT3 phosphorylation, however to various degrees." (PMID 19455144, 2009). "Notably, normal SVZ-derived cells underwent mTOR but not analogous Akt, Stat3 and p70S6K activation following high oxygen acute exposure, suggesting differences in oxygen sensitivity between tumour and normal cells." (PMID 19587783, 2009). "Interestingly, the positive LIF effect on tumor cell viability is not dependent on Stat3 activation, which inhibits tumor cell survival as it does in normal mammary epithelium." (PMID 17925034, 2007). "Therefore, targeting STAT3 and MUC1 interplay may be a strategy for enhanced anti-tumor efficacy." (PMID 40001578, 2025). "Notably, the levels of p-STAT3 and total STAT3 were significantly reduced in KPC tumor-bearing Xbp1mKO mice compared to corresponding Xbp1fl/fl mice suggesting that the IRE1α/XBP1 signaling mediates the activation of the JAK-STAT signaling in skeletal muscle of KPC tumor-bearing mice." (PMID 40655023, 2025). "Likewise, EP restrains tumor growth and metastasis in lymphoma, as well as hepatocellular and gastric carcinomas, by downregulating the HMGB1-RAGE axis and its downstream AKT/NF-κB and ERK/STAT3/SRC signaling pathways, thereby inhibiting proliferation and provoking cell death." (PMID 41465435, 2025). "Therefore, it is plausible that STAT3 activation in immune cells (such as T cells, dendritic cells, and macrophages) may enhance rather than suppress anti-tumor immune responses." (PMID 40426911, 2025). "Importantly, while we used genetic perturbations to interrogate the STAT3/β3 axis, we did not explicitly test whether pharmacologic inhibition of STAT3 can block tumor initiation or progression in vivo." (PMID 40701148, 2025).
tumor (continued). "Notably, STAT3 induces the expression of anti-apoptotic and pro-survival genes such as Bcl-2, Bcl-xL, survivin, PIM1, or MCL1, as well as extracellular matrix modulators like matrix metalloproteinases (MMPs), thereby supporting tumor growth, metastasis and chemoresistance." (PMID 41031165, 2025). "Additionally, proteins involved in the regulation of the cell cycle (e.g., ATM and STAT3), cell proliferation (e.g., LYN and SRRT), metabolism (e.g., GOT2, PPP1CA, and PYGB), and the regulation of Ca2+ flux (e.g., ANXA6 and CALM1) were also found phosphorylated in the tumor cells." (PMID 40129242, 2025). "JAK inhibitors may block STAT3 signaling, but they can inadvertently activate NF-κB in macrophages, leading to the secretion of pro-survival factors such as IL-6 and CSF2, which activate tumor cell STAT3 and PI3K signaling through paracrine mechanisms, forming an escape loop from treatment." (PMID 40936705, 2025). "Additionally, tumor-infiltrating B cells produce large amounts of lymphotoxin, a cytokine that belongs to the TNF family that contributes to activation of the IkB kinase α and STAT3-dependent pathway, which in turn increases the survival of androgen-deprived PC cells." (PMID 40136652, 2025). "Gr‐1+CD11b+ cells also promoted tumor angiogenesis through the G‐CSF/STAT3/prokineticin 2 (Bv8) axis, while anti‐BV8 treatment could significantly reduce the tumor volume and decrease the number of Gr‐1+CD11b cells and their activity, indicating the positive role of MDSCs in tumor angiogenesis." (PMID 40452814, 2025). "Moreover, astragalus achieves its inhibitory effect on the tumor ball formation and migratory capacity of HeLa cancer stem-like cells by inhibiting the protein expression levels of stemness markers (e.g., CD133, Oct4, Sox2, and Nanog), as well as STAT3 signaling." (PMID 40490812, 2025). "Additionally, signal transducer and activator of transcription 3 (STAT3) signalling within the TME reprogrammes these cytotoxic cells towards regulatory phenotypes, increasing CD73 expression and the release of immunosuppressive cytokines, thereby enhancing tumour immune evasion." (PMID 41194660, 2025). "STAT3 is highly expressed in both tumor and normal tissues, and STAT3 expression was expressed at a significantly higher concentration in non-neoplastic tissue samples compared to tumor tissue samples (mean log2 expression: 12.66; IQR: 12.4–12.7 vs. 11.91, IQR: 11.68–12; p = 0.0015)." (PMID 40426911, 2025). "Indeed, the study results presented here demonstrated that simultaneous inhibition of integrin αv, STAT3, and GSK3β using cilengitide, WP1066, and AR-A014418, respectively, synergizes with anti–PD-1 therapy and offers a complete tumor regression in about 50% of GBM tumor–bearing mice." (PMID 40131864, 2025). "IL-17/IL-17RA subsequently activated NF-κB pathway and STAT3 pathway, triggering the transcription of various downstream target genes, including PD-L1, Cyclin family members, MMPs, and EMT makers, which may lead to immune evasion, tumor growth, and tumor invasion of PCa." (PMID 40055805, 2025). "Additionally, SCs co-cultured with tumor cells can secrete high levels of IL-6, which promotes the migration and invasion of the cancer cells through the activation of STAT-3 signaling, however, it can be mitigated by neutralizing IL-6 or inhibiting STAT-3 expression." (PMID 40567365, 2025). "Although the peritumoral expression of p-STAT3 was higher in Dnajb4–/– mice, it shows minimal differences between the tumor sections of Dnajb4–/– and wild-type mice, suggesting another possibility that HLJ1 in the tumor regions may regulate tumor proliferation in a STAT3-independent manner." (PMID 39738726, 2024). "Additionally, considering the expanding clinical applications of tumor immunology, our review offers a more comprehensive understanding of the correlation between CMTM family and immunity, encompassing various mechanisms, including PD-L1/PD-1, EGFR, WNT, and JAK2/STAT3 pathways." (PMID 38223763, 2024).
tumor (continued). "After internalization, the intracellular concentrated ROS in tumor cells could trigger the instant transformation of the cationic CRP polymer to a neutral zwitterionic polymer for swift Cas9 and sgSTAT3 release, accompanied by Cas9 RNP reassembly to knock out the STAT3 gene in the genome." (PMID 38923275, 2024). "Additionally, the anti-tumor properties of NK cells return upon the activation of the nuclear factor erythroid 2-related factor 2 (Nrf2) antioxidant pathway, thus overriding the negative impacts of STAT3 activation on the immune cells." (PMID 38464736, 2024). "Thus, crosstalk between STAT3 and YAP activation may facilitate tumour progression." (PMID 37950040, 2024). "Tetraarsenic hexoxide (As4O6) could increase mitochondrial ROS generation by preventing STAT3 phosphorylation, causing caspase 3/GSDME‐dependent pyroptotic cell death and ultimately inhibiting tumor proliferation and metastasis in triple‐negative breast cancer cells." (PMID 37752941, 2023). "Interestingly, a single miR can play different roles in several tumor subtypes: miR-410-3p, for example, positively influencing proliferation and invasiveness in gonadotroph and corticotroph cells, increasing cyclin B1 levels, and activating MAPK, PTEN/AKT, and STAT3 signaling pathways." (PMID 37958702, 2023). "Thus, STAT3/IL-6 signaling may involve gankyrin-regulated crosstalk between tumor cells and nonparenchymal cells." (PMID 36660927, 2023). "However, independent studies confirm that its expression in the MDA-MB-231 cell line not only favors tumor growth but also promotes the Warburg effect and induces resistance to paclitaxel and inhibitory molecules of the PI3K/AKT/mTOR pathway through activation of JAK2/STAT3." (PMID 36901916, 2023). "In addition, recent evidence has shown that pentoxifylline inhibits tumor growth and angiogenesis by inhibiting IL-6 secretion and VEGF–VEGFR2 signaling via the STAT3 signaling pathway, which is associated with the non-classical proangiogenic stem cell factor (SCF)." (PMID 37190108, 2023). "Hence, these results suggested that loss of TMEM25 promotes cell growth or survival via activating EGFR/STAT3 signaling pathway, which may play a pivotal role in TNBC development, especially for the cells inside a tumor where with limited supply of growth factors." (PMID 37095176, 2023). "In addition, expression levels of STAT3 were also revealed to be correlated with DFI, PFI, and DSS of different tumor patients in K-M survival plots, and the univariate Cox hazards regression analysis results measured by OS, DFI, PFI, and DSS in forest plots were as well demonstrated." (PMID 36968603, 2023). "TNF-alpha signaling via NF-kB, IL6/JAK/STAT3 signaling, PI3K/AKT/mTOR signaling, MYC targets v2, TGF-beta signaling, and Kras signaling were mostly negatively correlated with LRRC3B expression, consistent with silencing of LRRC3B in tumor tissue, which may result in carcinogenesis." (PMID 36798137, 2023). "Furthermore, we found that DOKD inhibited CT26+ tumor cell growth by regulating inflammation, metastasis, and angiogenesis by activating the IL-17/TLR4/NF-κB p65 pathway and inhibiting the activation of the Src/HIF-1α/Erk1/2/Snail/N-cadherin/Vimentin/MMP9 and Erk1/2/HIF-1α/STAT3/VEGFA pathways." (PMID 37239383, 2023). "Due to its critical role during wound healing and regeneration, Stat3 also plays a central role during the initiation, maintenance, and progression of solid cancers, both as a neoplastic cell intrinsic driver and as a negative modulator of the anti-tumor immune response." (PMID 35053428, 2022). "However, TSM-Me could not effectively inhibit tumor cell viability and induce STAT3 degradation compared with TSM-1." (PMID 36509291, 2022). "However, a blockade of the Stat3 pathway may result in an impairment of tumor immune surveillance, and inhibition of the Stat3 pathway did not affect normal cell survival." (PMID 36140747, 2022).
tumor (continued). "Notably, the absence of NHERF2 in vivo decreases STAT3 activation and tumor growth, which means that NHERF2 may be a potential target for cancer treatment." (PMID 36286020, 2022). "Moreover, STAT3 downstream of EGFR signaling pathway could promote the transcription of UTX, suggesting an “EGFR-STAT3-UTX” axis that participates in the progression of NSCLC, and can at least partly explain the higher levels of UTX in NSCLC tumor tissues comparing to normal samples." (PMID 34661759, 2022). "Additionally, PBA-Niclo-SLNs significantly inhibited STAT3, TNBC stem cell populations (CD44+/CD24−), and EMT (epithelial–mesenchymal transition) markers along with increased tumor-site accumulation with significant tumor regression and enhanced survivability of TNBC-bearing mice." (PMID 36077466, 2022). "In addition, activation of the STAT-3 and NF-κB signaling pathways stimulates the expression of vascular endothelial growth factor (VEGF) and chemokines (CXC), induces epithelial-to-mesenchymal transition, and ultimately promotes tumor cell proliferation and growth." (PMID 36406359, 2022). "Finally, pathway analysis revealed that IL-37-signaling mediators, such as STAT3, are crucial partners of PD-1, PD-L1, and CTLA-4 pathways, providing hints for an interfering role of this cytokine in the immune-checkpoint blockade of anti-tumor immune responses." (PMID 36551790, 2022). "The expression of STAT3 is not related to gender (OR = 0.88, 95% CI (0.54, 1.44), p = 0.609), age (OR = 0.54, 95% CI (0.21, 1.36), p = 0.191), capsular invasion (OR = 2.98, 95% CI (0.23, 38.29), p = 0.403), or tumor multiplicity (OR = 0.25, 95% CI (0.003, 19.28), p = 0.533)." (PMID 35463085, 2022). "The relationship between STAT3-dependent inhibition of autophagy and PROM1 (cytosolic) expression is novel and may provide valuable insights into GBM tumorigenesis and help identify new molecular markers that are predictive of GBM tumor recurrence and chemoresistance." (PMID 40396025, 2022). "However, circMALAT1 (hsa_circ_0002082) acts as a proto-oncogene or tumor-suppressor gene, and circMALAT1 can inhibit the translation of the tumor-suppressor gene PAX5 and also act as a sponge of miR-6887-3p, activate the JAK/STAT3 signaling pathway and promote the self-renewal of cancer stem cells." (PMID 36006268, 2022). "However, the expression levels of both forms of STAT3 were not correlated with tumor grade." (PMID 35836213, 2022). "Chol-DsiSTAT3 polyplexes and Chol-siSTAT3 polyplexes suppress STAT3 mRNA in primary 4T1 tumors for a similar duration after IV administration of a single equimolar dose that does not saturate the primary 4T1 tumor [0.50 mg Chol-DsiSTAT3/kg and 0.41 mg Chol-siSTAT3/kg], (ii)." (PMID 35076584, 2022). "Therefore, it is not surprising that STAT3 has emerged as a promising tumor therapeutic target." (PMID 36232344, 2022). "Thus, inhibiting STAT3 to block tumor growth without affecting STAT1 is a challenging task." (PMID 33805945, 2021). "Thus, STAT3 may provide a link between both miR-202 and miR-26a and NSCLC tumor progression." (PMID 34440757, 2021). "Inhibition of JAK/STAT3 or PI3k/AKT/mTOR pathways, which have shown potential therapeutic implications in DLBCL, may also ultimately impact PD-L1 expression in the tumour cells, providing additional rationale for future clinical evaluation with PD-1/PD-L1 blockade combinations." (PMID 34572910, 2021). "Similarly, we established a subcutaneous tumour model and a liver metastasis model in vivo, and we found that bufalin inhibited the growth and metastasis of CRC by significantly reducing the number of blood vessels and amount of STAT3 phosphorylation in vascular endothelial cells." (PMID 34496870, 2021).
tumor (continued). "Moreover, the authors further determined that the association is dependent on STAT3/ALDH1 signaling regardless of endogenous A-FABP level, suggesting a dual mechanism by which A-FABP supports tumor progression both as a fatty acid transporter and as a signaling molecule." (PMID 33987528, 2021). "Furthermore, all tumor analyses showed negative STAT3 correlations with tumor purity." (PMID 33668805, 2021). "Moreover, PS-acet.-STAT3, but not PS-unacet.-STAT3 or PS-STAT3-K685R peptide, effectively inhibited STAT3 phosphorylation, transcriptional regulation, and tumor progression (proliferation marker Ki-67 and angiogenesis marker CD31)." (PMID 33491667, 2021). "Moreover, the implementation of STAT3-targeting therapies must consider the marked heterogeneity of CAFs and they should be tailored towards suppressing tumor-promoting populations while preserving those that do not contribute to disease to essentially promote an anti-tumor response in the TME." (PMID 34858425, 2021). "In addition, we observed the lower expression of STAT3 and Ki-67 in tumor tissues in the stattic treatment group, and the much lower expression levels in the circUBE2Q2 shRNA combination group than in the negative control mouse tumor tissues via IHC." (PMID 34611143, 2021). "Furthermore, tumor releases GM-CSF and IL-6 promotes the conversion of myeloid cells to an MDSC phenotype, mainly through the activation of a CCAA T-enhancer-binding protein β(C/EBP β)-mediated program that implicates the downstream blockade of STAT3 for terminal differentiation." (PMID 34527668, 2021). "Interestingly, recent studies show tumor cells can reprogram NK cells to gain immunosuppressive functions [e.g., increase IL-10 and transforming growth factor-β (TGF-β) production via signal transducer and activator of transcription 3 (STAT3) transcriptional activity, suppressing IFN-γ production]." (PMID 32351498, 2020). "STAT-3 activation or secretion ofinflammatory agents occurs by proto-oncogenes activation, tumor-suppressorgenes, chromosomal rearrangement, and other genomic alterations in tumor cells.Unexpectedly, there is no inherent confirmation for triggering the mutations inSTAT-3 itself." (PMID 32167126, 2020). "Although transcription factors, C/EBPβ, STAT3, and TAZ, have been shown to be able to induce mesenchymal transition in glioblastoma, it has been unknown whether these factors trigger the mesenchymal transition in a cell autonomous manner or by indirectly modifying the tumor microenvironment." (PMID 32341445, 2020). "The demonstrated interaction with STAT3, accompanied by its reduction of transcriptional activity, further suggests that SH2D4A is linking STAT3 to its mitochondrial functions, and inhibition of PHB-interaction may have therapeutic effects in tumor cells with STAT3 activation." (PMID 33257655, 2020). "Inflammation may enhance tumor initiation by expanding the CSC population, yet the molecular pathways linking inflammation to tumor initiation are poorly understood except for the suggested involvement of a handful of molecules, including STAT3, NF-κB, and Wnt/β-catenin." (PMID 33115754, 2020). "However, STAT3 and 5 were not or were only weakly reduced in this particular tumor cell line." (PMID 31861612, 2019). "Also, survival data is highly influenced by the response of patients to their treatment and may not always reflect all mechanistic links between STAT3/5 activity and tumor biology." (PMID 31557897, 2019). "Their subsequent studies identified that G-CSF via activation of STAT3 promoted NB tumorigenicity and metastasis, raising the possibility that small molecule inhibitors of the JAK/STAT pathway that were being developed for other cancers may selectively target these highly aggressive NB tumor cells." (PMID 31803140, 2019).